S100A4 (S100 calcium binding protein A4)
Diseases named in the same sentence as S100A4 in open-access papers (continued):
Sharing a sentence is not in itself a finding about the gene and the disease.
cancer (373 papers, 2000 to 2025). A tumor composed of atypical neoplastic, often pleomorphic cells that invade other tissues. "Studies in the context of cancer associated myeloid derived suppressor cells (MDSCs) show that S100A4 directly bind to TLR4, suggesting a direct effect in RA as well." (PMID 40078995, 2025). "Thirdly, the underlying mechanism by which cancer cells promote PD-L1 expression in response to S100A4 stimulation requires further investigation." (PMID 40772225, 2025). "The genetic variants were similar to the original tumor tissue, and they owned expression of cancer-associated fibroblast (CAF) markers (FSP1/S100A4, Vimentin) and nuclear translocation β-catenin." (PMID 40299526, 2025). "S100A4 is among the most extensively studied member of this family due to its strong association with inflammation, cancer, and neurodegeneration." (PMID 40078995, 2025). "Amongst them, S100A4 stands out as a member that is strongly implicated in a wide range of pathologies ranging from cancer to chronic inflammatory conditions." (PMID 40078995, 2025). "Another study demonstrated that FGF2/FGFR1 mediate triple-negative breast cancer (TNBC) cells to upregulate and secret S100A4 to adapt vascular endothelial cells and trigger motility of cancer-associated fibroblasts." (PMID 38609357, 2024). "In ovarian cancer cells, the overexpression of MLLT11 was also associated with an activation of WNT/beta-catenin/S100A4 oncogenic signals, resulting in malignant tumor progression and metastasis formation and reduced sensitivity to cancer therapy." (PMID 38203610, 2023). "Subsequently, the E#4 was defined as lymphatic endothelial (LEC) cells by the marker genes (LEC) (e.g., PDPN and PROX1), and E#1 was defined as carcinoma‐associated fibroblasts derived endothelial cells (CAFsEc) (e.g., S100A4)." (PMID 37726969, 2023). "Comprehensive bioinformatics analyses for the identification of the deleterious nonsynonymous mutations were performed for the S100A4 gene, which are reported to play a significant role in cancer and other pathophysiological diseases." (PMID 35965620, 2022). "S100a4 is an epithelial-mesenchymal transition mediator associated with the maintenance of cancer-initiating cells in HNSCC20." (PMID 34785704, 2021). "S100A4 has been reported to be highly expressed in various cancers and is usually associated with a poor prognosis." (PMID 33789743, 2021). "To explore the underlying mechanism of this process, we looked to S100A4, which has been reported to be a critical regulator of the cell cycle, differentiation and invasion in many kinds of cancer cells." (PMID 33789743, 2021). "S100A4 protein is also expressed by macrophages, fibroblasts, and activated lymphocytes, and has been implicated in cancer biology and in inflammatory diseases." (PMID 32564509, 2020). "As a metastasis-associated protein and marker of the EMT, S100A4 contributes to the progression of several types of cancer." (PMID 32842846, 2020). "Together suggest that in the vicinity of GemOE cells, MSCs differentiate into S100A4-secreting cancer-associated fibroblasts (i.e., CAFs, step 2)." (PMID 31844158, 2019). "Enhanced cell growth and motility, associated with elevated S100A4 expression, was shown to increase the metastatic potential of cancer cells among a variety of malignancies, such as breast cancer, lung cancer, or CRC." (PMID 30927479, 2019). "We next examined S100A4 secretion by an enzyme-linked immunosorbent assay (ELISA) specific for human S100A4 protein with CM from cancer cells." (PMID 31667000, 2019). "Elevated levels of S100A4 in carcinoma cells promote metastasis and are associated with reduced survival of cancer patients, including OSCC." (PMID 30970087, 2019). "The expression of the calcium-binding protein S100A4 has been reported to be associated with poor prognosis in various cancers." (PMID 31526392, 2019).
cancer (continued). "To study this fundamental aspect of NMII function, we overexpressed two S100A4 variants in A431 human epithelial carcinoma cells." (PMID 31652274, 2019). "S100A4 contains two EF-hands calcium-binding motifs and is considered to associate with the progression of various cancers such as: Colon; breast; prostate; gallbladder; gastric; lung; and melanoma." (PMID 30037057, 2018). "The overexpression of S100A4 in cancer cells is closely linked to the aggressive phenotype and metastatic behavior of human cancers, and has been associated with poor survival of cancer patients." (PMID 29069865, 2017). "This review summarized up to date advancement on the role of S100A4 in human cancer development, progression, and metastasis and the underlying molecular events and then strategies to target S100A4 expression experimentally." (PMID 29069865, 2017). "The expression of S100A4 in the nucleus was associated with poor survival and cancer metastasis of CRC patients." (PMID 29069865, 2017). "Our study also identified S100A4 as the first cancer-associated target of miR-505-5p and its functional impact on metastasis-associated characteristics like migration and invasion." (PMID 28423501, 2017). "Given the relation of S100A4 overexpression to progression, the association of S100A4 with risk of BMs in patients with known cancer was investigated." (PMID 27100728, 2016). "There is a body of evidence that S100A4 protein is associated with the development of several cancers and particularly with their ability to metastasize." (PMID 25359220, 2014). "The associations between S100A4 levels, inflammation, disease activity, muscle strength and cancer development were evaluated." (PMID 25359220, 2014). "At the molecular and cellular level, the cancer-promoting properties of S100A4 are caused by regulating cell motility, proliferation, apoptosis, and by stimulation of angiogenesis and remodelling of the extracellular matrix." (PMID 25359220, 2014). "S100A4 protein is associated with Ca2+-dependent regulation of intracellular activities and is significant in the invasion, growth and metastasis of cancer." (PMID 24944689, 2014). "A large number of experimental studies have linked the S100A4 gene product to the metastatic phenotype of cancer cells." (PMID 24188373, 2013). "Filament assembly of nonmuscle myosin IIA (NMIIA) is selectively regulated by the small Ca2+-binding protein, S100A4, which causes enhanced cell migration and metastasis in certain cancers." (PMID 22483112, 2012). "In this direction, an inverse correlation has been established between the expression levels of S100A4 and E-Cadherin and has been associated with poor differentiation of cancer cells." (PMID 20515499, 2010). "S100A4 was linked to cancer cell invasiveness and metastasis in various human cancer types and in vivo cancer models." (PMID 18718015, 2008). "The S100A4 protein has been associated with increased metastatic capacity of cancer cells, but how S100A4 exerts the metastasis-promoting effects is still incompletely understood." (PMID 15318945, 2004). "Two members of the S100 gene family, S100A6 and S100A4 have been suggested to be associated with cancer invasion and metastasis." (PMID 10952782, 2000). "In summary, these data support a working model where, across disease states such as cancer, fibrosis, and chronic inflammation, S100A4 regulates pathogenic macrophage polarization to an M2-like, alternatively activated state with immunosuppressive and profibrotic functions." (PMID 40078995, 2025). "In addition, chromatin complexes expelled from nuclei of apoptotic cancer cells activate the RAGE receptors on neighboring surviving cancer cells, boosting the expression of metastasis-associated protein S100A4, which enhances their migration and invasiveness." (PMID 40132886, 2025).
cancer (continued). "While S100A4 is a well-established epithelial-mesenchymal transition marker implicated in metastasis across multiple malignancies, emerging evidence reveals its complex, context-dependent roles in cancer biology." (PMID 40853920, 2025). "S100A4 expression in cancer is highly associated with T cell exhaustion and immunosuppression." (PMID 40078995, 2025). "S100A4 is associated with the pathogenesis of different cancers, amongst them also PCa." (PMID 38721756, 2025). "Additionally, interaction of NMII-A with S100A4 has been mechanistically implicated in cancer metastasis." (PMID 38072048, 2024). "An abnormal expression and activity of S100A4 is associated with various types of cancer." (PMID 36232334, 2022). "Additionally, detection of markers for the cancer-associated fibroblasts, S100A4/Fsp-1, and α-SMA indicated that ablation of MMP14 in fibroblasts does not reduce the amounts of these cells around tumors." (PMID 33924099, 2021). "Although S100A4 is a strong predictor of poor survival in cancer patients, whether S100A4+ TAMs are associated with prognosis and survival of patients with cancer remains unknown." (PMID 34145030, 2021). "In GBM, S100A4 was reported to be associated with the migration and invasion of cancer cells." (PMID 35069135, 2021). "Overexpression of the S100A4 gene was first associated with the occurrence, development, and prognosis of breast cancer, gastric cancer, rectal cancer, lung cancer, melanoma, and other cancers." (PMID 32596158, 2020). "S100A4 is a calcium-binding protein associated with invasion and metastasis of cancer cells." (PMID 30970087, 2019). "S100A4, also known as Mts1, is a member of the S100 calcium-binding protein family and has been associated with carcinogenesis and tumor development and progression in various types of cancers, including PC." (PMID 30621039, 2019). "Cancer progression is associated to extracellular S100A4’s autocrine and paracrine functions." (PMID 30041429, 2018). "In addition, human and porcine myofibroblasts express S100A4 proteins which have been demonstrated to be implicated in cancer cell migration." (PMID 30315177, 2018). "Therefore, S100A4 expression in CRC tissues was evaluated as a biomarker for risk of cancer metastasis." (PMID 29069865, 2017). "Thus, this review systematically summarizes the functions and roles of S100A4 in human cancer development, progression, and metastasis as well as the underlying molecular events and strategies to target S100A4 expression experimentally." (PMID 29069865, 2017). "The S100A4 protein, a member of the S100 family, has been associated with cancer metastasis." (PMID 27679610, 2016). "S100A4 (metastasin-1), a metastasis-associated protein and marker of the epithelial to mesenchymal transition, contributes to several hallmarks of cancer and has been implicated in the progression of several types of cancer." (PMID 27127879, 2016). "S100A4 is associated with cell migration and invasion; key steps in cancer metastasis." (PMID 24932473, 2014). "To examine the potential significance of this SNP in cancer cell migration and anticancer drug resistance, we next examined whether cancer cells expressing this S100A4 protein variant showed changes in their metastasis-related properties." (PMID 25310523, 2014). "In addition, co-culturing cancer cells with fibroblasts and expression of miR-21 induced the expression of the cancer associated fibroblast (CAF) marker S100A4." (PMID 24039846, 2013). "S100A4, a member of the S100 protein family, is involved in several steps of the metastatic cascade and is associated with patient outcome in various types of cancer." (PMID 24215488, 2013).
cancer (continued). "The inhibition of S100A4 expression or function can reduce the malignancy caused by enhanced S100A4 protein levels and, if used in clinical application, may increase the metastasis free survival of cancer patients." (PMID 22878175, 2012). "The function of S100A4 as an oncoprotein may be associated with several important molecules involved in growth, invasion and metastasis of cancer cells." (PMID 22200787, 2012). "Several studies have associated the S100A4 protein with increased metastatic capacity of cancer cells, and more recently a correlation between the level of S100A4 protein and prognostic outcome has been reported in various types of cancer (lung gall bladder, oesophageal, gastric, breast and colon)." (PMID 12799648, 2003). "The S100A4 protein has been associated with increased metastatic capacity of cancer cells, and recent studies have suggested a correlation between the expression level of S100A4 and the prognostic outcome for patients with various types of cancer." (PMID 12799648, 2003). "Moreover, microglia conditioned with medium from ZBTB18 expressing cells showed a strong reduction of S100A4, a small calcium binding protein that is associated with poor prognosis in various cancers, and which has been linked to EMT and GBM mesenchymal transition." (PMID 39516530, 2024). "In addition, nuclear expression of S100A4 is associated with cancer metastasis of CRC patients." (PMID 33691630, 2021). "Considering these facts, our cocktail could be activating cancer-related signaling pathways that might cause an increase in the expression of some pluripotency genes, but especially in those closely related to invasion and metastasis, such as S100A4." (PMID 33805347, 2021). "In conclusion, unraveling the complex interactions between S100A4 and the immune system can open new avenues for therapeutic interventions in cancer, fibrosis, and pro-inflammatory conditions." (PMID 40078995, 2025). "The field has since evolved in its understanding of how S100A4 promotes multiple aspects of cancer progression through immune modulation and cancer cell aggressiveness." (PMID 40078995, 2025). "S100A4 has been found to be commonly dysregulated in a variety of cancers including breast, liver, and ovarian cancers." (PMID 41173847, 2025). "This review focuses on recent advances in the understanding of S100A4 function in immune cells, comparing and contrasting S100A4 regulation of immune responses in cancer and chronic inflammatory diseases." (PMID 40078995, 2025). "The Gepia online database revealed a significant difference in the expression of ALDH1A1 and S100A4 between ovarian normal tissues and cancer." (PMID 40093000, 2025). "We provide evidence that S100A4 regulation of immune cell function has a profound role in promoting the pathogenesis of cancer and pro-inflammatory conditions." (PMID 40078995, 2025). "For example, a recent study demonstrated that DNA-bound S100A4 was released from dying cancer cells to promote metastatic function in neighboring cancer cells via the RAGE pathway." (PMID 40078995, 2025). "In the context of cancer, S100A4 has been shown to promote metastasis, the epithelial-mesenchymal transition, and immune suppression." (PMID 40078995, 2025). "To this point, we have focused on the roles of S100A4 in regulating different immune cell types in normal and pathological contexts such as cancer." (PMID 40078995, 2025). "To test this, we looked for correlations between S100A4 expression and proliferation, susceptibility to apoptosis, mobility, and epithelial–mesenchymal transition (EMT)/cancer stem cell (CSC) features in OCCC cells." (PMID 39857966, 2025). "Specifically, S100A4 and PDPN are proteins that exhibit high expression in cancer-associated fibroblasts, while Cytokeratin (CK) stains the epithelial regions and DAPI stains adenine–thymine-rich regions in DNA." (PMID 41073772, 2025).
cancer (continued). "B: PCR detection of TGFβI and S100A4 expression in HCC, TGFβI and S100A4 were highly expressed in cancer tissues." (PMID 40821652, 2025). "Given its major role in promoting the progression of cancer, fibrosis, and chronic inflammatory conditions, there are ongoing efforts to develop inhibitors to target S100A4 signaling." (PMID 40078995, 2025). "Conditioned by CDCP1-high SW480 or HCT116 cells, CAFs displayed a protumor phenotype with upregulation of α-SMA, FAP, PDGFRβ, and S100A4, indicating that cancer-cell CDCP1 promotes fibroblast activation." (PMID 41301830, 2025). "While many studies have focused on S100A4 function within cancer cells to promote cancer progression and cancer stem cell function, a growing body of evidence indicates that S100A4 signaling serves multifaceted roles in the innate and adaptive immune systems." (PMID 40078995, 2025). "The spatial map of module I aligns well with the cancer regions, as well as the spatial expression of module-associated genes such as KRT17, TM4SF1, and S100A4, which have been reported as PDAC markers." (PMID 40033360, 2025). "The most promising inhibitors identified were tested for S100A4 transcriptional inhibition, their impact on wound healing, migration, proliferation and viability of cancer cells." (PMID 40765817, 2025). "This study demonstrates that splicing factor proline and glutamine rich (SFPQ) is present on the cell surface in cancer cells, where it interacts with S100A4 and so forth proteins to alter cell function when SFPQ is a nuclear protein normally." (PMID 40770831, 2025). "Meanwhile, TGFβI and S100A4 mRNA expression showed a positive correlation trend in both cancer and adjacent tissues (P<0.05)." (PMID 40821652, 2025). "In conclusion, these results highlight how S100A4 expression in T cells can polarize T cells into pathogenesis-promoting states, consistent across chronic-inflammatory diseases and cancer." (PMID 40078995, 2025). "This review focuses on the biology of S100A4 in various immune cell subtypes and examines S100A4 activities in the contexts of immune responses in cancer, autoimmunity, and fibrosis." (PMID 40078995, 2025). "The levels of p-STAT3 and S100A4 were significantly decreased in RP11-54O7.17 overexpressed cells, whereas carcinoma cell viability and S100A4 expression were dose-dependently reduced after transcription of different concentrations of RP11-54O7.17 in vitro." (PMID 41173847, 2025). "As a result, S100A4 has been widely studied in the context of cancer, where it has been shown to stimulate cell migration and the formation of metastasis, hence its name of metastasin." (PMID 39766257, 2024). "Among these markers are fibroblast proteins like vimentin and S100A4, whose expression is elevated in cancer." (PMID 38606999, 2024). "S100A4 functions in the extracellular milieu as a liaison between cancer cells and the surrounding microenvironment to mediate proinflammatory response." (PMID 39830522, 2024). "S100A4, also known as metastasin, is well-documented for its role in promoting metastasis in various cancers, including CRC." (PMID 39205741, 2024). "To investigate the mechanism behind ANXA9’s ability to transfer the S100A4 out of cancer cells, we treated BC cells with okadaic acid (a phosphatase inhibitor) to increase ANXA9 phosphorylation." (PMID 38609357, 2024). "Extracellular ATP is synthesized by S100A4 in cancer cells and fibroblasts, facilitating the migration and metastasis of BC cells, although the specific concentrations are not elucidated in the immunological context of relevant studies." (PMID 39555060, 2024). "S100A4 has also been shown to play an important role in cancer cell proliferation, metastasis, and invasiveness." (PMID 38072048, 2024).